DLGAP1 (DLG associated protein 1)
Description:
Part of the postsynaptic scaffold in neuronal cells.
Synonyms: DAP-1; SAPAP1; DAP1; GKAP; DAP-1-ALPHA; DAP-1-BETA; DLGAP1A; DLGAP1B
Tractability: Antibody: its Gene Ontology location is reachable by antibodies, with high confidence; UniProt places it where antibodies can reach, with medium confidence. PROTAC: UniProt records ubiquitination sites on it; ubiquitination databases record sites on it; its protein half-life has been measured.
Gene: Protein-coding gene on chromosome 18 (3,496,032 to 4,455,307, reverse strand). Ensembl gene ENSG00000170579.
Subcellular location: Cell membrane; Postsynaptic density; Synapse
Subcellular location (Human Protein Atlas): Cytosol; Vesicles
Pathways (Reactome):
Neuronal System: Neurexins and neuroligins
Gene Ontology:
Molecular function: protein binding; molecular adaptor activity; protein-containing complex binding
Biological process: chemical synaptic transmission; modulation of chemical synaptic transmission; signaling
Cellular component: glutamatergic synapse; plasma membrane; postsynaptic specialization; postsynaptic density; synapse
Genetic constraint (gnomAD): Loss-of-function variants: 11 observed, 81.45 expected, observed/expected ratio (o/e) 0.14, 90% interval 0.084 to 0.22. The upper end of that interval is the gene's LOEUF score, 0.22, which puts it in group 1 of 6, group 1 being the genes least tolerant of losing a copy. Missense variants: 1,048 observed, 1,312.2 expected, observed/expected ratio (o/e) 0.8, 90% interval 0.76 to 0.84. Synonymous variants: 558 observed, 530.75 expected, observed/expected ratio (o/e) 1.05, 90% interval 0.98 to 1.13.
Homologues: Orthologues: chimpanzee DLGAP1 (99% identical), macaque DLGAP1 (99% identical), dog DLGAP1 (98% identical), rabbit DLGAP1 (98% identical), pig DLGAP1 (97% identical), rat Dlgap1 (96% identical), mouse Dlgap1 (96% identical), guinea pig DLGAP1 (94% identical), tropical clawed frog dlgap1 (81% identical), zebrafish dlgap1a (72% identical), zebrafish dlgap1b (68% identical). Paralogues in human: DLGAP2 (52% identical), DLGAP4 (48% identical), DLGAP3 (41% identical), DLGAP5 (14% identical).
Diseases named in the same sentence as DLGAP1 in open-access papers:
DLGAP1 is named in the same sentence as 47 diseases in open-access papers, as found by Europe PMC text mining. Sharing a sentence is not in itself a finding about the gene and the disease. The quoted sentences say what the papers report.
schizophrenia (18 papers, 2010 to 2024). A major psychotic disorder characterized by abnormalities in the perception or expression of reality. "Genetic variations of DLGAP1 are known to be associated with several psychiatric disorders, such as obsessive–compulsive disorder, schizophrenia, and major depressive disorder." (PMID 34593835, 2021). "Rare missense mutations of the DLGAP1 were detected in patients with schizophrenia before, while common polymorphisms of the DLGAP1 influenced the executive function in attention deficit hyperactivity disorder." (PMID 34659328, 2021). "Genetic Dlgap1 variants are associated with neuropsychiatric disorders, including schizophrenia, autism spectrum disorder, and obsessive-compulsive disorder." (PMID 32169116, 2020). "Our findings are consistent with observations that individuals affected by schizophrenia or ASD carry rare genetic variants that are predicted to reduce the function of DLGAP1." (PMID 29396406, 2018). "Rodent studies have shown that DLGAP1 protein complexes isolated from the hippocampal CA1 region are enriched in proteins considered risk factors for schizophrenia and ASD16,17." (PMID 29396406, 2018). "Our data suggest that Dlgap1 knockout leads to PSD disruption and reduced sociability, consistent with reports of DLGAP1 haploinsufficient variants in schizophrenia and ASD." (PMID 29396406, 2018). "As explained in section 6, DLGAPs influence NMDA receptor synaptic scaling via DLG4 and both DLG4 and DLGAP1 have been linked to schizophrenia." (PMID 28870203, 2017). "DLGAP1–4 proteins have also been linked to a variety of neurological disorders including schizophrenia, autism spectrum disease (ASD), trichotillomania, obsessive compulsive disorder (OCD) and cerebellar ataxia." (PMID 28870203, 2017). "These include GFOD1, which is associated with attention deficit hyperactivity disorder (ADHD), DLGAP1 which is associated with schizophrenia, DOCK9 associated with bipolar disorder, and SORCS1 which is associated with memory." (PMID 24151499, 2013). "Thus, emerging data suggests that genetic variants increasing DLGAP1 function may predispose to OCD, while variants decreasing DLGAP1 function might predispose to schizophrenia or ASD." (PMID 29396406, 2018). "More research and data is expected in the coming years to clarify the role of DLGAP1, 2, 3 and 4 in synaptic plasticity and their involvement in schizophrenia and neurological diseases." (PMID 28870203, 2017). "Specifically, there is heavy literature on involvement of DLGAP1 in schizophrenia and suggesting DLGAP2 as a candidate gene for ASD and PTSD." (PMID 28870203, 2017). "After the discovery of the potential role of DLGAP1 in schizophrenia, related gene family members have also been analysed extensively in genetic studies." (PMID 28870203, 2017). "In this context, Dlgap1 KO mice exhibited disruption of protein interactions in PSD and sociability deficits, consistent with the findings of DLGAP1 haploinsufficient variants in schizophrenia and ASD." (PMID 36831241, 2023). "Gain-of-function variants of DLGAP1 have been associated with obsessive-compulsive disorder (OCD), while haploinsufficient variants have been linked to autism spectrum disorder (ASD) and schizophrenia in human genetic studies." (PMID 29396406, 2018). "The schizophrenia-related upregulation of DLGAP1 expression could be the result of a feedback mechanism where the neurons are trying to re-establish the normal function and signalling of the GluN2A containing NMDA receptor." (PMID 28870203, 2017). "We evaluated Dlgap1 wild type (WT), heterozygous (HT), and knockout (KO) mice for protein interactions within the PSD, and behavioral phenotypes relevant to OCD, ASD, and/or schizophrenia." (PMID 29396406, 2018).
schizophrenia (continued). "Although Dlgap1 HT and KO mice showed reductions in sociability, but not other behavioral abnormalities observed in schizophrenia or autism patients such as PPI deficits, reduced DLGAP1 function may still contribute to risk for these disorders." (PMID 29396406, 2018). "Furthermore, we identified a DLGAP1 missense mutant (DLGAP1F70L) in 1 of 98 patients with schizophrenia, but not in a subsequent collection of 468 patients and 533 healthy controls, suggesting that DLGAP1F70L might be a patient-specific rare mutation." (PMID 33343614, 2020).
autism spectrum disorder (8 papers, 2010 to 2023). A spectrum of developmental disorders that includes autism, and Asperger syndrome. "In humans, genetic variants of DLGAP1-4 have been linked with neuropsychiatric conditions, including autism spectrum disorder (ASD)." (PMID 30664629, 2019).
obsessive-compulsive disorder (5 papers, 2017 to 2025). A disorder characterized by the presence of persistent and recurrent irrational thoughts (obsessions), resulting in marked anxiety and repetitive excessive behaviors (compulsions) as a way to try to decrease that anxiety. "DLGAP1 interacts with the glutamate receptor GRIK2, also implicated in obsessive-compulsive disorders." (PMID 29045412, 2017). "Despite variants in the Dlgap1 gene having the two lowest p-value in a genome-wide association study of obsessive compulsive disorder (OCD), previous studies reported the absence of OCD-like phenotypes in Dlgap1 knockout (KO) mice." (PMID 39177810, 2025).
attention deficit-hyperactivity disorder (4 papers, 2018 to 2024). A disorder characterized by a marked pattern of inattention and/or hyperactivity-impulsivity that is inconsistent with developmental level and clearly interferes with functioning in at least two settings (e.g. at home and at school). "Studies have shown that Dlgap1, a postsynaptic density protein gene, can affect the executive function of attention-deficit hyperactivity disorder." (PMID 39635132, 2024).
Anxiety (3 papers, 2018 to 2025). Intense feelings of nervousness, tension, or panic often arise in response to interpersonal stresses. "A role for Abl2, Csmd2, Dlgap1, and Isl1 in neurodevelopment and psychiatric and neurodegenerative diseases have been reported in previous studies and our association analysis suggests a role in anxiety." (PMID 33431988, 2021). "This study showed that genetic deletion of Dlgap1 in mice caused late development of OCD-like phenotypes including skin lesions, excessive self-grooming and anxiety-like behavior, which was responsive to treatment with fluvoxamine." (PMID 39177810, 2025). "The reductions in sociability were highly specific, with no changes in locomotor activity, anxiety, sensorimotor gating, depression-like behaviors, or nest-building observed in Dlgap1 KO mice." (PMID 29396406, 2018).
bipolar disorder (3 papers, 2013 to 2024). A disorder of the brain that causes unusual shifts in mood, energy, activity levels and the ability to carry out day-to-day tasks. "Dlgap1, Trank1, and Tafa5 are established risk genes for neuropsychiatric diseases, with Dlgap1 specifically related to major depressive disorder, Trank1 associated with bipolar disorder, and Tafa5 linked to depressive-like behaviors." (PMID 39272155, 2024).
depression (3 papers, 2015 to 2024). "Our results indicating normal interactions between SHANK3 and Homer1 in Dlgap1 KO mice is consistent with the absence of any depression-related phenotype in these mice, including lack of effects in the FST and sucrose preference test." (PMID 29396406, 2018).
coronary artery disease (2 papers, 2016 to 2022). "DLGAP1 has also been previously associated with levels of cardiac troponin T measured by a highly sensitive assay (hs-cTnT), where hs-cTnT has been found to be associated with diabetes mellitus in patients with stable coronary artery disease." (PMID 27695091, 2016).
gout (2 papers, 2018 to 2022). A condition characterized by painful swelling of the joints, which is caused by deposition of urate crystals. "The serum urate-raising and gout risk allele rs7188445_G associates with increased expression of DLGAP1." (PMID 30719032, 2018).
Obesity (2 papers, 2012 to 2020). Accumulation of substantial excess body fat. "This study identifies a new function of the Dlgap1 gene in regulating the browning of white fat, laying a foundation for the alleviation and treatment of obesity." (PMID 32169116, 2020). "Because both obesity and type 2 diabetes are characterized by imbalances in energy metabolism in the human body, Dlgap1 may play an unidentified common role in both conditions." (PMID 32169116, 2020).
type 2 diabetes (2 papers, 2020 to 2022). "Certain Dlgap1 genetic variants are underrepresented in patients with type 2 diabetes in the Netherlands and Korea." (PMID 32169116, 2020). "Additionally, Dlgap1 functional variants or genetic variants of neighboring genes that have strong linkage disequilibrium with Dlgap1 could be responsible for both browning and type 2 diabetes." (PMID 32169116, 2020). "Dlgap1 is involved in type 2 diabetes, the development and maintenance of normal brain function, and interaction with the motor protein dynein." (PMID 32169116, 2020).
acute megakaryoblastic leukemia (1 paper, 2019). Acute megakaryoblastic leukemia (AMKL) is a form of acute myeloid leukemia (AML) that occurs predominantly in childhood and particularly in children with Down syndrome (DS-AMKL). "Detailed Immunofluorescent analysis of the native DLGAP1 indicated that in centrosomal regions it is organized in small granules resembling centriolar satellites, as shown in the childhood acute megakaryoblastic leukemia cell line M-O7e." (PMID 31321035, 2019).
behavioural disorders (1 paper, 2015). "Finally, many genes associated with neurological development and behavioural disorders were pinpointed (CACNG2, CALN1, ACCN3, EFNB3, DLGAP1 and ATP1B2)." (PMID 26100250, 2015).
colorectal tumor (1 paper, 2014). "The decreased DLGAP1 expression in tumor is mainly due to hypermethylation and that DLGAP1 might play a growth-suppressive role in colorectal tumor." (PMID 24871302, 2014).
Developmental delays (1 paper, 2017). "Developmental delays and craniofacial anomalies associated with a loss of genetic material at the NRG3 locus, accompanied by a gain of material at the DLGAP1 site, have also been reported." (PMID 29045412, 2017).
erythroleukemia (1 paper, 2019). Acute erythroid leukemia characterised by the presence of at least 50% erythroid precursors and at least 20% myeloblasts in the bone marrow. "Since K562 cells arose from a CML associated erythroleukemia, we examined relative levels of DLGAP1 mRNA in a database at the FHCRC of patient samples in all the phases of CML as well as normal CD34 cells." (PMID 31321035, 2019).
Hypertension (1 paper, 2021). The presence of chronic increased pressure in the systemic arterial system. "We identified a novel locus at chromosome 18p11.31 (DLGAP1) associated with resistant hypertension that reached genome-wide significance." (PMID 34593835, 2021). "Our novel findings suggest a possible role of DLGAP1, which may contribute to susceptibility to resistant hypertension, possibly via the central nervous system, leading to a new target for drug discovery in the future." (PMID 34593835, 2021).
invasive breast carcinoma (1 paper, 2019). A carcinoma that infiltrates the breast parenchyma. "Another fusion transcript of Rab31 was detected in a patient with invasive breast carcinoma and was originated by the fusion form of DLGAP1-Rab31." (PMID 31083279, 2019).
Lymphatic Metastasis (1 paper, 2025). Transfer of a neoplasm from its primary site to lymph nodes or to distant parts of the body by way of the lymphatic system. "Only 6 genes, namely CHGA, CHGB, PCSK2, PCSK1N, DLGAP1 and DLGAP3 were down-Regulated in the lymphatic metastasis group." (PMID 41431044, 2025).
myeloid leukemia (1 paper, 2019). A clonal proliferation of myeloid cells and their precursors in the bone marrow, peripheral blood, and spleen. "The centrosomal DLGAP1 localization is equally important as centrosomal aberrations, which are a common feature in most solid tumors, are frequently observed in MPN, and in myeloid leukemia." (PMID 31321035, 2019).
myopia (1 paper, 2019). "DLGAP1 also is one of nine genes located in a chromosomal region (myopia-2, MYP2) that demonstrated significant genetic linkage with autosomal dominant high myopia." (PMID 31367973, 2019).
resistant hypertension (1 paper, 2021). "We identified a novel candidate locus at the DLGAP1 gene with susceptibility to resistant hypertension with genome-wide significant levels, and 18 loci, including CYP11B2 and CACNA1D, as having suggestive association with resistant hypertension in the Japanese population." (PMID 34593835, 2021). "Our GWAS findings, combined with pathway analyses, provide an insight that the DLGAP1 protein at the postsynaptic membrane in the central nervous system may contribute to driving resistant hypertension, and highlight the importance of the nervous system in the etiology of resistant hypertension." (PMID 34593835, 2021). "However, this validation study was not successful in reproducing the DLGAP1 results observed in our GWAS for resistant hypertension." (PMID 34593835, 2021).
retinitis pigmentosa 55 (1 paper, 2024). "Both DLGAP1 and DLG1 are associated with retinitis pigmentosa 55, a disorder characterized by photoreceptor loss and reactive pigment changes in the RPE starting in the mid-peripheral fundus." (PMID 39337590, 2024).
tumor (7 papers, 2013 to 2025). "The expression level of DLGAP1 was significantly downregulated by overexpression of miR‐148 in Fadu cell, while upregulation of DLGAP1 plays a tumor‐suppressing role in Fadu cells." (PMID 29905017, 2018). "The DLGAP1 expressions in tumor tissues were downregulated for about 50% compared with adjacent normal tissues (P < 0.01)." (PMID 29905017, 2018). "Five hypermethylated loci harbored by four genes (GSTP1, TACSTD2, BMP4 and RASSF1) and three hypomethylated loci in three genes (ARHGAP8, GPR35 and DLGAP1) were validated using 7 assays with 12 tumor-normal tissue pairs from this study." (PMID 23437062, 2013). "HOTAIRM1 was confirmed as a tumor suppressor via sponging miR‐148a and promote the expression of DLGAP1, which could be regarded as an important target for the prevention and treatment of HNT." (PMID 29905017, 2018).
cancer (6 papers, 2015 to 2024). A tumor composed of atypical neoplastic, often pleomorphic cells that invade other tissues. "A recent evidence of a direct DLGAP1 involvement in oncogenic processes comes from studies by Li at al, where DLGAP1 was established as a modifier of invasive cancer growth driven by NMDAR signaling." (PMID 31321035, 2019).
neurological diseases (4 papers, 2017 to 2024). "DLGAP1 was also implicated in Alzheimer’s and other neurological disorders, where as a direct substrate of CDK5, it undergoes phosphorylation and proteasomal degradation leading to synaptic actin remodeling and ultimately to a synapse loss." (PMID 31321035, 2019). "We also review the link of DLGAP1–4 to the various neurological disorders." (PMID 28870203, 2017). "Although the effect of DLGAP1 in HNT has not been clearly studied, it has been proved that DLGAP protein family was linked to their function in the brain and involvement in neurological diseases." (PMID 29905017, 2018).
infection (2 papers, 2012 to 2020). The state of being infected such as from the introduction of a foreign agent such as serum, vaccine, antigenic substance or organism. "Genes in regions associated with control of infection included a zinc finger cluster (ZNF192, ZSCAN16, ZNF389, and ZNF165; P = 0.001), C19orf42/TMEM38A (P = 0.047), and DLGAP1 (P = 0.092)." (PMID 23082221, 2012).
head and neck tumor (1 paper, 2018). "This study is aimed to explore the regulatory effect of lncRNA HOTAIR/miR‐148a/DLGAP1 axis on head and neck tumor (HNT) cell growth, cell mobility, and invasiveness." (PMID 29905017, 2018).
DLGAP1 also shares sentences with these, for which no sentence is quoted: psychiatric disorder (5 papers); Alzheimer disease (2); autism (2); diabetes (2); atrial fibrillation (1); cognitive deficits (1); fragile X syndrome (1); glioma (1); glomerular disease (1); heart failure (1); melanoma (1); mental retardation (1); metastatic melanoma (1); myeloid malignancies (1); neuroblastoma (1); neurodegenerative disease (1); neurodevelopmental disorder (1); pancreatic tumor (1); Tourette syndrome (1).